CRP (C-reactive protein)
Diseases named in the same sentence as CRP in open-access papers (continued):
Sharing a sentence is not in itself a finding about the gene and the disease.
Obesity (continued). "C-reactive protein (CRP), an established biomarker of inflammation, is commonly elevated in people with overweight/obesity." (PMID 36467859, 2022). "Apparently, inflammatory cytokines are able to induce IR in both adipose tissue and muscle.in case of obesity, adipocytes produce plenty of cytokines such as TNF-α and IL-6, the primary stimulator of the production of CRP in the liver." (PMID 35318405, 2022). "Correction for multiple comparisons using the Bonferroni test showed significant differences between children with obesity and those with normal weight in the levels of platelets, iron parameters, uric acid, triglycerides, HDL-C, LDL-C, globulin, and CRP." (PMID 36498548, 2022). "Accordingly, abnormal circulating levels of TNF-α, IL-6, C-reactive protein (CRP) and leptin have been found in individuals with obesity, reflecting their overexpression in adipose tissue." (PMID 35565781, 2022). "Proinflammatory cytokines—such as interleukin (IL)-8, tumor necrosis factor-alpha (TNF-α) and other proteins as C-reactive protein (CRP)—are increased in cardiovascular disease (CVD), type II diabetes and obesity." (PMID 35529460, 2022). "A controlled clinical trial evaluated the anti-inflammatory and antioxidative effects of OEA (250 mg/day) on obesity, as well as assessing LPO, TAC, CRP, IL-6, and TNF-α levels." (PMID 36120593, 2022). "Levels of CRP, uric acid, LDL-C and lymphocytes were higher among children with overweight and obesity." (PMID 36498548, 2022). "It is therefore important to provide aggressive lifestyle change in individuals with prediabetes, obesity, metabolic syndrome, high triglyceride, low HDL-C, and high CRP." (PMID 35509100, 2022). "For BMI-based obesity, the probability of MHO was highest, followed by MuHO, and increased for every unit increase in the hs-CRP value, especially for the Arab group." (PMID 35267891, 2022). "Obesity generates a proinflammatory state through the secretion of inflammatory mediators including tumor necrosis factor (TNF)-a and C-reactive protein (CRP)." (PMID 36687448, 2022). "Linking these cardiometabolic diseases is a state of low-grade inflammation, with higher cytokines and c-reactive protein levels found in individuals with NAFLD, obesity and type II diabetes." (PMID 35736447, 2022). "Significant differences were found between participants with obesity and those with overweight in the levels of transferrin saturation, vitamin B12, HDL-C, and CRP." (PMID 36498548, 2022). "In cases of obesity, the adipocytes secrete pro-inflammatory cytokines such as TNF-α and IL-6, which stimulate the liver’s production of CRP, altering the hosts’ immune response, and increasing their susceptibility to bacterial infections." (PMID 36661547, 2022). "Studies have demonstrated that subjects with obesity have elevated circulating pro-inflammatory cytokines, including tumor necrosis factor-α (TNF-α), interleukin-6 (IL-6) and C-reactive protein (CRP)." (PMID 35252310, 2022). "Pregnant women with obesity or GDM have increased maternal inflammation and elevated hs-CRP compared to normal pregnant women, and suppression the inflammation helps improving pregnancy outcomes and maternal complications." (PMID 34030674, 2021). "In the children with obesity group, ALT and BChE levels correlated with anthropometric measurements, insulin resistance, and lipid parameters, leptin, interleukin-6, CRP, and sICAM-1 while BChE levels negatively correlated with adiponectin." (PMID 33665176, 2021). "In contrast, SM (OH)s, SM (2OH)s, and GSLs exhibited favorable correlations with obesity (rs = −0.07 to −0.19), triglycerides/HDL-cholesterol (rs = −0.08 to −0.20), CRP (rs = −0.08 to −0.14), adiponectin (rs = 0.06 to 0.15), and RBP4 (rs = −0.06 to −0.15)." (PMID 34208976, 2021). "In particular, three studies found an association between vegetable and fruit intake and lower levels of CRP, and IL-6 and TNF-α, both in healthy males and females, as well as in males and females with obesity." (PMID 33503979, 2021).
Obesity (continued). "Median CRP values were significantly higher in patients with T2DM (9.5 vs. 6.5 mg/L, p = 0.043) and super-obesity (12.0 vs. 6.6 mg/L, p = 0.023)." (PMID 33026590, 2021). "In our study, upregulated NEU1 offset the effects of miR-23b-3p on body weight, fat percent, FBG, FI and AUC of both OGTT and ITT, and inflammatory factors (CRP, IL-6, TNF-α, MCP1) in mice with obesity-induced IR." (PMID 33781239, 2021). "Classical proinflammatory cytokines, such as C-reactive protein (CRP), TNF-α, and IL-6, are biomarkers of obesity-related chronic inflammation." (PMID 33815885, 2021). "It has been reported that AST and obesity are independent predictors of biliary pancreatitis in children and that HCT, CRP and BMI are useful predictors of severe pancreatitis." (PMID 34178894, 2021). "Among individuals with high CRP free of CVD, those with obesity have higher CRP and higher coronary artery calcium scores and carotid artery intima thickness." (PMID 34760952, 2021). "The pro-inflammatory marker, C-reactive protein (CRP), is also increased in both obesity phenotypes compared to lean individuals." (PMID 34684461, 2021). "Acupuncture significantly downregulated the serum levels of CRP, TG, CHO, LDL, leptin, and prostaglandin E and upregulated the serum levels of HDL in rats with simple obesity." (PMID 34646336, 2021). "A bidirectional relationship might exist between obesity-related traits and MDD with atypical features, as a large international consortium study showed that patients with atypical depression carried a higher number of genetic risk variants for disturbances in BMI, CRP and leptin." (PMID 33653423, 2021). "In addition, people with obesity have a decreased concentration of adiponectin, which has anti-inflammatory properties, and an increased concentration of leptin, which has pro-inflammatory properties, as well as an increase in acute phase agents such as C-reactive protein (CRP) and amyloid antigen." (PMID 34960696, 2021). "In particular, the circulating GLP-1 concentration was highly correlated with obesity (as estimated by BMI and WC), BP, and HOMA-IR, as well as with hs-CRP, an inflammatory marker." (PMID 33800785, 2021). "C-reactive protein (CRP), as one of the inflammatory factors with a significant positive correlation with obesity, was also included." (PMID 33859706, 2021). "Circulating C-reactive protein, a marker of inflammation, is a predictor of CVD and is higher in people with obesity, in particular centripetal adiposity." (PMID 34760952, 2021). "Prior to interruption, TRT resulted in improvements in residual voiding volume, bladder wall thickness, CRP, AMS, IIEF-EF, IPSS and obesity parameters, while PSA and prostate volume increased." (PMID 34552788, 2021). "Numerous factors could elucidate the relationship between obesity and anxiety, one of which is immune-inflammatory stimulation, as both conditions increase inflammatory biomarkers, such as C-reactive protein (CRP), interleukin-6 (IL-6) and tumour necrosis factor-alpha (TNF-α)." (PMID 33962601, 2021). "This study sought to examine the seasonal impacts on CRP in breast cancer survivors to determine whether the pattern of seasonal change for CRP would vary by past smoking intensity, cardio-metabolic health condition, obesity status, and intakes of red meat, vegetables, and fruits." (PMID 33562354, 2021). "Another two studies found an association between adherence to both a hypocaloric low and a hypocaloric high glycaemic index diet and lower levels of high sensitivity c-reactive protein (hs-CRP) in males and females with obesity." (PMID 33503979, 2021). "It was also positively associated with inflammation reflected in white blood cell count, CRP, and LBP as well as metabolic markers related to obesity and insulin resistance such as HOMA-IR, HbA1c, FPG, FPI, and uric acid." (PMID 34158092, 2021). "We also observed that the interaction of CRP SNP rs1130864 and rs3093059 with obesity on IMT, hs-CRP and fibrinogen levels." (PMID 32214403, 2020).
Obesity (continued). "In humans, increase of a marker of inflammation, C-reactive protein, induced by obesity has been correlated with increased incidence of obesity in offspring and suggests this inflammation may be involved in the prenatal programming of ingestive behavioral changes that leads to obesity." (PMID 33324346, 2020). "A cross-sectional analysis comparing CACS, inflammatory marker hs-CRP, and visceral fat burden among four obesity phenotypes (MHNO, metabolically unhealthy non-obesity (MUNO), MHO, and metabolically unhealthy obese (MUO)) was performed." (PMID 33383705, 2020). "Our study showed that obesity may generate chronic inflammation in children as early as in prepubescence, as indicated by significantly higher serum concentrations of calprotectin, chemerin, and CRP in these children as compared with children of normal body weight." (PMID 33081030, 2020). "Our results provide evidence for the main effects of the FGB genes on IMT, for the interaction of CRP SNP rs1130864 and rs3093059 with gender on IMT, and with obesity on IMT, hs-CRP and fibrinogen levels." (PMID 32214403, 2020). "Relationships between higher levels of maternal inflammation markers (e.g., CRP or IL-6 and TNF-alpha inflammatory cytokines) and higher birth weight and obesity in the offspring have also been observed." (PMID 32213887, 2020). "Serum levels of inflammatory markers, such as C-reactive protein (CRP), tumor necrosis factor α (TNF-α), and interleukin 6 (IL-6), correlate with body mass index across the broad range of obesity." (PMID 33266499, 2020). "The increased AT levels of TLR8 in obesity and T2DM were confirmed to be positively correlated with inflammatory markers like C-reactive protein and the expressions of inflammatory cytokines and chemokines." (PMID 32684073, 2020). "CRP levels are reduced when COX-2 action is inhibited, suggesting that obesity-related aromatase activity in breast tumorigenesis correlates with inflammation." (PMID 33614510, 2020). "Levels of C-reactive protein, HDL and LDL-cholesterol correlated with obesity related neurostructural alterations." (PMID 33173508, 2020). "Serum IL-6 and C-reactive protein (CRP) levels were significantly increased in high fat diet-induced obese mice, demonstrating an increased inflammation in obesity condition." (PMID 32825589, 2020). "However, CRP alone may not sufficiently capture the effect of diet on the complete inflammatory phenotype associated with obesity." (PMID 33256114, 2020). "This could be due to the so‐called chronic inflammation of obesity, deriving from stimulation of inflammatory mediators through adipose tissue and resulting pro‐inflammatory state and oxidative stress, and finally an increase in CRP (Ellulu, Patimah, Khaza'ai, Rahmat, & Abed, 2017)." (PMID 31702104, 2020). "Significant gene-gender and obesity interaction on ln IMT, ln hs-CRP, and fibrinogen in recessive model#." (PMID 32214403, 2020). "An increase in the levels of pro-inflammatory cytokines and proteins such as interleukin-6 (IL-6), tumor necrosis factor alpha (TNF-α), leptin or C-reactive protein (CRP) in both blood and adipose tissue itself was observed as obesity progressed." (PMID 32555600, 2020). "The adverse levels of HDL-C, hs-CRP and HOMA-IR in individuals with severe obesity are consistent with the findings from other studies." (PMID 32522176, 2020). "In obese subjects (n = 173), the degree of obesity and BMD were related to IL-6 levels (in males), osteocalcin (in females), C-reactive protein (CRP), and leptin indicating that adiposity and systemic inflammation are associated with low BMD." (PMID 30792697, 2019). "The very new finding of our investigation was in determining the following factors affecting gut integrity in psoriasis: obesity (BMI), disease severity (PASI score) and systemic inflammation (NLR, CRP)." (PMID 31336842, 2019). "In this context, we examined the relationship between CRP and incident T2DM in relation to obesity and hypertension." (PMID 30872696, 2019).
Obesity (continued). "Logistic regression analysis showed that there were seven independent risk factors for 1-year mortality in CAP patients, namely, age, cardiovascular disease, cerebrovascular disease, obesity, APACHE II score, level of CRP and CAP severity." (PMID 31291389, 2019). "Serum levels of C-reactive protein (CRP) directly correlate with insulin resistance and carotid intima-media thickness (cIMT) in children and adolescents with overweight and obesity." (PMID 31824900, 2019). "There was a positive association for IL-6 and CRP in both sexes according to obesity (in the adjusted analysis); women who were obese in ≥ 2 follow-ups were associated with a mean IL-6 of 2.45 and a CRP of 3.74 compared to IL-6 of 1.21 and CRP of 1.29 for those with no exposures (adjusted analysis)." (PMID 31071114, 2019). "Compared with the study population, this group had a higher fraction of women, a higher prevalence of obesity and current smokers, lower PCS and MCS scores for both sexes, higher CRP levels, and fewer using OC among women." (PMID 30921429, 2019). "In this framework, recent studies have demonstrated that obesity might be strongly associated with low-grade chronic inflammation, which is accompanied by raised concentrations of inflammatory cytokines, including IL-6 and TNF-α, and acute phase proteins, such as C-reactive protein (CRP)." (PMID 31635199, 2019). "Thus, based on the systemic inflammatory state associated to the obesity, the oocyte maturation is variably affected by the altered balance of driver hormones as SHBG with other soluble factors including insulin, glucose, lactate, triglycerides, and C reactive protein." (PMID 29523133, 2018). "Thus, the observed CRP levels might have been due to the known low-grade chronic inflammation associated with obesity rather than CVD." (PMID 30647800, 2018). "Significant differences in smoking, obesity, waist circumference, fasting glucose, and HDL cholesterol were observed according to serum hs-CRP level." (PMID 30186371, 2018). "Increased platelet counts (PCs) and high concentrations of circulating C-reactive protein (CRP) have been observed in conditions with chronic inflammation such as the metabolic syndrome, as well as obesity, possibly due to secondary thrombocytosis." (PMID 29222767, 2018). "Obesity, impaired IS or T2DM are characterized by low-grade inflammation frequently assessed by CRP as well as interleukin 6 (IL-6) or tumor necrosis factor alpha (TNFα)." (PMID 30294302, 2018). "Furthermore, while CRP was used with α1GP to correct ferritin levels for inflammation, as CRP is an acute phase reactant, the measurement of hsCRP would have strengthened the ability of this study to assess the true level of inflammation in individuals with chronic inflammation, such as in obesity." (PMID 29329258, 2018). "Obesity confers an odds ratio between 1.7 and 2.2 for VTE, likely acting through higher CRP levels found in subjects with higher BMI, in addition to potential for decreased physical activity." (PMID 29876337, 2018). "The subjects with overweight were similar to the subjects with obesity, except for fasting glucose, WBC, hs-CRP, ALT and γ-GT." (PMID 30458048, 2018). "Cross-sectional studies have shown that many individuals with obesity and/or MDD have elevated levels of cytokines, including interleukin (IL)-6, tumor necrosis factor (TNF)-α and C-reactive protein (CRP)." (PMID 29176959, 2017). "Several authors have studied the relationship between AHI and hs-CRP levels in OSA patients, but the results are contradictory, possibly due to the role of obesity." (PMID 28831208, 2017). "Further prospective research is needed to determine the relation of CRP and other inflammatory markers to the development and progression of FMS in the presence of the potentially complex roles of obesity and comorbidities." (PMID 28687081, 2017).
Obesity (continued). "The only two overweight subjects showed a mean decrease of 34% and 23%, respectively, for CRP and TNF-α levels, while, among women with obesity (BMI > 30 kg/m2), mean increase of 39% and 5% was present, respectively." (PMID 28408969, 2017). "There was a significant correlation between hs-CRP, IL-6 and TNF-α with measures of obesity such as BMI and WC." (PMID 29099041, 2017). "C-reactive protein (CRP), interleukin (IL) 6, IL-8, and tumour necrosis factor alpha (TNF-α) were higher in the obesity group compared with the normal-BMI group." (PMID 28771179, 2017). "Therefore, in the absence of sportive activity, obesity indices could be positively associated with CRP levels." (PMID 28487812, 2017). "We found a significant negative correlation between serum TAC and ox-LDL concentrations (r = −0.27, p < 0.05) and positive correlation between CRP and TAC concentrations (r = 0.36, p < 0.05) in children with obesity." (PMID 28904738, 2017). "Obesity is a major determinant of LGI and increased levels of CRP can predict the development of type 2 diabetes, metabolic syndrome, and insulin resistance." (PMID 27701463, 2016). "As obesity is a low-grade inflammation, and EA has shown to have an anti-obesity effect, we measured important inflammatory markers such as TNF-α, IL-6 and CRP, in our patients, during EA treatment." (PMID 27136447, 2016). "Using multivariate regression analysis, obesity was identified as an independent factor for a high BDNF AUC index after adjustment for age, CRP, and PC 2 hours glucose." (PMID 27787389, 2016). "Levels of CRP and ESR were higher in obesity with IR versus lean (6.83 ± 5.65, 17.46 ± 11.67, P < 0.001; resp)." (PMID 27239101, 2016). "Therefore, the absence of association between serum hs-CRP levels and sarcopenia and obesity groups among females in our study may be due to the low prevalence of chronic hepatitis and of unobserved confounding factors." (PMID 26177029, 2015). "Transcripts altered by a Western diet that were examined in FHS were also compared to circulating levels of CRP and IL6, inflammatory markers shown to be increased in individuals with CVD, obesity, and a Western diet." (PMID 26148065, 2015). "Hall and colleagues measured level of CRP and myeloid-related protein-8/14 (MRP-8/14) in patients with OSAS and investigated the relation between obesity and inflammatory parameter." (PMID 26075263, 2015). "In addition, obesity may also induce chronic low-grade inflammation resulting in an alteration of local and systemic levels of cytokines (e.g., interleukin-6, C-reactive protein) and adipokines (e.g., leptin, adiponectin), which may play a role in bladder carcinogenesis to bladder cancer mortality." (PMID 25803438, 2015). "One study showed that BMI was the only predictor of hs-CRP levels and TNF-α levels (all P<0.001), considering that obesity induced an increase in certain inflammatory markers in the serum." (PMID 26087062, 2015). "The results of a systematic review and meta-analysis of 51 cross-sectional studies showed a positive correlation between C-reactive protein (CRP) and obesity as assessed by waist circumference, BMI or waist to hip ratio." (PMID 26644890, 2015). "Previous studies suggest there is low-grade inflammation in obesity along with altered levels of several circulating factors, such as increases in the plasma levels of TNF-α, CRP, IL-6, and other biological markers of inflammation." (PMID 26699936, 2015). "In our study, total LPC as well as a number of LPC species not only correlate negatively with BMI but also with CRP, possibly indicating a role of LPC as a marker of inflammation in obesity." (PMID 25340546, 2014). "Whereas plasma levels of the short pentraxin CRP are higher in obese individuals and those with metabolic syndrome, evidence linking PTX3 with obesity and metabolic syndrome remains scant." (PMID 24705587, 2014).